TLR2 (toll like receptor 2)
Diseases named in the same sentence as TLR2 in open-access papers (continued):
Sharing a sentence is not in itself a finding about the gene and the disease.
infection (continued). "Moreover, TLR-2 stimulation polarizes IL-10 production causing persistence of infection." (PMID 33238997, 2020). "Therefore, aberrant vitamin D signaling could be a major contributing factor to the hyper-susceptibility phenotype of tlr2 mutants in Mm infection." (PMID 31747871, 2019). "Furthermore, TLR2 coordinating with other PRRs and interacting with PAMPs from C. sinensis may influence host iNOS/NO responses and susceptibility to infection." (PMID 28784165, 2017). "However, IL-6 and TNF-α expression in infected wild-type DCs decreased significantly with DenV2 infection, in comparison with infected TLR2-deficient DCs (227 ± 16 vs. 178 ± 11 for IL-6 MFI in BL/6 and TLR2 KO; 259 ± 9 vs. 218 ± 11 for TNF-α MFI in BL/6 and TLR2 KO)." (PMID 29285314, 2017). "TLR2 is important in the recognition of pathogen or tissue-damage derived molecules as part of the innate immune response, and binds a variety of endogenous molecules called Damage Associated Molecular Patterns (DAMPs) released during infection, inflammation or as a result of tissue damage." (PMID 26784349, 2016). "Although TLR2 has been implicated in the response to infection mediated by TLR2 ligands, includes molecules with diacyl and triacylglycerol moieties, proteins and polysaccharides, scanty data is available on the direct relationship between TLR2 and iron overload." (PMID 26999096, 2016). "Thus, TLR2 has a vital role in protection against infections caused by S. aureus that produce PSMs." (PMID 27470911, 2016). "The importance of TLRs in innate resistance to T. gondii was demonstrated by MyD88-/- mice being acutely susceptible as IL-12-/- mice to infection with avirulent strains of the parasite, and both TLR2 and TLR4 receptors may participate in the host defense against T. gondii infection." (PMID 26528819, 2015). "The quantitative effect of this infection was large, with modelling results indicating that the highest levels of louse reproductive activity (>20 louse egg cases per host) were associated with approximately 50% reductions in TLR2 and TLR9-mediated TNF-α responses." (PMID 19386086, 2009). "In addition, whereas overall S. pneumoniae PLN elicited less profound histopathological alterations in lung tissue than S. pneumoniae D39, the difference in total lung histology scores between TLR2 KO and WT mice was especially clear after infection with the pneumolysin-deficient strain." (PMID 17711480, 2008). "Finally, the survival of TLR2-deficient mice after infection with B. pseudomallei suggests that TLR2-mediated dysregulation of the immune system in response to invasive B. pseudomallei might cause septic melioidosis." (PMID 17676990, 2007). "Previously, TLR2 KO mice were found to be less susceptible to lethal infections with Yersinia enterocolitica or Candida albicans through a mechanism that likely involved a stronger type 1 cytokine response due to diminished production of the prototypic type 2 cytokine IL10 during infection." (PMID 17676990, 2007). "Ex vivo infection experiments show that the protective Tlr2 haplotype produces a stronger proinflammatory response to B. afzelii compared to the haplotype associated with susceptibility." (PMID 42052896, 2026). "Infection with avirulent BS103 Shigella primed the NAIP–NLRC4 inflammasome in a TLR2- and MYD88-dependent manner." (PMID 41533441, 2026). "Natural infection by orthoflavivirus typically triggers viral entry pathways (e.g., via the TLR2 pathway) with the assistance of vector salivary proteins, which modulates local host immunity and facilitates infection." (PMID 41596370, 2026). "In CL patients, TLR2 expression tends to be high at the beginning of the infection but decreases as the infection progresses." (PMID 41500977, 2026). "Infection of these chimeras with Shigella resulted in much higher IEC CFU burdens as compared to the control Tlr2/4/Unc−/−:CD45.1 chimeras, indicating that the production of IL-12p40 depends on active TLR signaling within the same cell." (PMID 40885187, 2025).
infection (continued). "The expression levels of TLR2 were upregulated at 4 h post-infection and further increased at 8 h post-infection in all infected groups." (PMID 40574283, 2025). "An in vitro infection of murine BMDMs isolated from TLR2-, TLR3- TLR4-, TLR7-, TLR9-, TLR2/TLR4-, and TLR2/TLR4/TLR9- deficient mice and cultured with Mtb showed that TLR9 was critical for protection against infection via FLT-3 ligand-generated DCs." (PMID 41236793, 2025). "Platelet TLR2 plays important roles in multiple diseases, including infection, thrombosis, inflammation, autoimmunity, cancer, neurodegenerative disorders, and metabolic conditions." (PMID 40137296, 2025). "For instance, in infection models, TLR2 facilitates CXCR4 expression and function through physical co-association and cross-talk, enhancing downstream signaling that promotes migration and inflammation." (PMID 41451130, 2025). "At 8 h post-infection, similar TLR2 expression levels were observed between UV strain 2020WUSS080 and HV+ strain 2020WUSS075 infected groups, which were significantly higher than those of the groups infected with HV+ stains ID24665, ID48908, and GX169." (PMID 40574283, 2025). "Transcription factor responsible for TLR2/4 expression, downregulated during infection to disrupt immune response." (PMID 40028182, 2025). "A mechanism has been proposed that varying levels of TLR2 activation by arenaviruses in the endosome affects the outcome of infection based on the resulting level of proinflammatory cytokine signaling." (PMID 40022100, 2025). "As a member of the TLR family, TLR2 was found to respond to infection by A. fumigatus conidia or mycelium in both mouse and human cells." (PMID 40597229, 2025). "Further observations also found that while both rKaSPI and rAdSPI promoted TLR-4 expression, T. spiralis infection also involves the regulation of TLR-1 and TLR-2 expression, highlighting the complexity of the parasite’s infection mechanism." (PMID 39799330, 2025). "We have previously demonstrated that HSPCs use TLR2 and Dectin-1 to sense Candida albicans to induce the production of trained monocytes/macrophages to fight against secondary infection." (PMID 40359412, 2025). "Members of the PE/PPE protein family are known to interact with an array of surface receptors to benefit infection, notably TLR2 and TLR4 (15, 53, –, 56)." (PMID 40787981, 2025). "This review examines the literature on the impact of specific polymorphisms in TLR2 and TLR4 on fungal recognition and infection." (PMID 41295183, 2025). "Together, these data highlight an important role for TLR2 mediating P. melaninogenica-induced protection against S. aureus adherence and infection." (PMID 41198444, 2025). "Infections with these two species in animal models induced immune responses involving the TLR2 or TLR4 signaling pathways, which enable pathogen sensing for innate immunity." (PMID 41277474, 2025). "PPE18 is required by Mtb to establish an effective infection in vivo and has been identified as an interacting antigen of Toll-like receptor 2 (TLR-2) to inhibit pro-inflammatory immune responses." (PMID 40787981, 2025). "At 4 h post-infection, the TLR2 expression levels in groups infected with UV and HV+ strains were significantly higher than that of the group infected with strain P1/7." (PMID 40574283, 2025). "Platelet TLR2 not only contributes to hemostasis and thrombosis but also plays a crucial role in infection, inflammation, and immune regulation." (PMID 40137296, 2025). "Vaccinated calves controlling the infection inside focal lesions displayed increased numbers of intestinal macrophages immunolabeling TLR2 and M1 polarization of the granulomas." (PMID 40646740, 2025). "The gene transcripts with the greatest number of shared correlations with PRRs across all three infections were PLAUR (with TLR2, RIG-I, LGP2) and SERPING1 (with TLR5, RIG-I, MDA5, and LGP2)." (PMID 40825056, 2025).
infection (continued). "Infection with S. aureus leads to increased Toll-like receptor 2 (TLR2) expression as part of the innate immune system." (PMID 40137369, 2025). "In platelets, PLAUR was positively associated with TLR2, TLR4, TLR8, and RIG-I, and with infection these associations changed to TLR7 and LGP2 but continued to correlate with TLR4 and TLR8." (PMID 40825056, 2025). "While DENV-2 infection-induced up-regulation of TLR2 and TLR7 mRNA during the early stages of infection (1.5 and 3 h.p.i), the mRNA expression of TLR2, TLR3, TLR4, TLR7, and TLR8 reaches its maximum peak of expression at 24 h.p.i." (PMID 40934228, 2025). "Conversely, TLR2 expression was downregulated following infection, potentially indicating an evolved resistance mechanism to prevent tissue infiltration by Gram-positive pathogens." (PMID 40453956, 2025). "Consistent with previous studies, we observed a significant increase in the expression of Tlr2, Myd88 and Nod2 after infection, indicating that both types of E. faecium can activate these signalling pathways." (PMID 38951957, 2024). "•Ad-induced TLR2-dependent NF-κB activation is significantly inhibited 24 h post-infection by E4 proteins." (PMID 38205184, 2024). "The MAC-infection-mediated downregulation of Snhg15 seen in wild-type BMDMs was suppressed in BMDMs derived from Tlr2 knockout mice." (PMID 38711507, 2024). "Among 35 articles, some of the studies demonstrated the response of TLR4 and TLR5 along with the TLR2 response during the infection of Leptospira spp./cell components." (PMID 39729468, 2024). "Long-term post-MHV-1 infection was associated with increased protein levels of HIF1-α, TLR-2, and EGFR, as revealed by immunoblot investigations." (PMID 38672267, 2024). "A prior study showed that neutralization of TLR2 and TLR4 on monocytes from patients with CL caused them to be less susceptible to in vitro infection and generate lower amounts of oxidants, upon incubation with L braziliensis." (PMID 38912968, 2024). "Here, we report that TLR2-dependent NF-κB activation in Ad5-infected cells was significantly inhibited 24 h post-infection." (PMID 38205184, 2024). "The in-vitro studies observed a TLR2 gene expression within 48 hours of infection, showing the response in the early stage of the disease." (PMID 39729468, 2024). "During infection, TLR2 and TLR4, which are members of the TLR family, are widely recognized as the most important pattern recognition receptors because they can be activated by multiple antigens." (PMID 38716051, 2024). "We also discovered that infection with S. aureus intensifies skin inflammation by enhancing IL-33 release from keratinocytes, and this is dependent on both TLR2 signaling and the necroptotic pathway." (PMID 38319737, 2024). "TLR2 has been shown to play a protective role during infections by triggering a strong pro-inflammatory response." (PMID 39080852, 2024). "During the initial stages of infection, TP lipoproteins activate dendritic cells (DCs) and macrophages through Toll-like receptor 2 (TLR2)-dependent signaling pathways." (PMID 38694502, 2024). "Differential expression of the TLR2 gene was observed in mice renal cells upon the infection of L. interrogans Copenhageni." (PMID 39729468, 2024). "These analyses revealed that while TLR2 mRNA expression was increased upon infection with both H. pylori strains, levels on the cell surface were significantly diminished compared to untreated DCs." (PMID 39288239, 2024). "In human and in-vivo studies, TLR2 response was observed within 7 days of infection, which is a longer period than that observed in in-vitro studies (2 days)." (PMID 39729468, 2024). "To study the potential role of TLR2 in DC activation upon infection with the ADP-heptose deficient H. pylori mutant, we first monitored TLR2 expression levels." (PMID 39288239, 2024). "Double knockout mice (DKO)(TLR2-/-,TLR4-/-) were very susceptible to infection, while all the wild-type mice(WT) and TLR2 -/- mice survived." (PMID 39729468, 2024).
infection (continued). "The findings indicated elevated levels of IL-9 and TLR2 in patients with CE, with the activation of the signaling pathway significantly increased as the duration of infection progressed." (PMID 39199394, 2024). "These analyses revealed that after 1 h of infection, TLR2 is found on the cell surface but also inside the cell upon H. pylori wt and mutant infection." (PMID 39288239, 2024). "Particularly, mixed-species infection increased the expression of TLR2/4, Nox2/4, and Toll/IL-1R domain-containing adaptor proteins such as MyD88 and TRAF6." (PMID 38700089, 2024). "Our mechanistic investigations revealed that TLR2 promotes H. pylori uptake and the enhanced CD40 expression upon infection with the ADP-heptose deficient H. pylori mutant." (PMID 39288239, 2024). "As a future research direction, it is worth collecting the patient samples to observe the response of the direct TLR2 at specific time points after the infection of Leptospira spp., though it is difficult to acquire those samples in a clinical setup." (PMID 39729468, 2024). "TLR2 is believed to play a protective role during early infection as it triggers a strong proinflammatory response, which is considered beneficial for bacterial clearance." (PMID 38891741, 2024). "Nevertheless, there seemed to be a small but noticeable increase in the co-staining of EEA1 with TLR-2 in LCMV-ARM-infected cells compared to LCMV-WE or mock infection." (PMID 38675975, 2024). "Recent research has demonstrated that infection with E. granulosus leads to a notable upregulation of TLR2 and IL-9 expression." (PMID 39199394, 2024). "Here, we found that infection of DCs with Mycobacterium tuberculosis (Mtb) triggers HIF1A-mediated aerobic glycolysis in a TLR2-dependent manner, and that this metabolic profile is essential for DC migration." (PMID 38922679, 2024). "Live and heat-inactivated L. reuteri KBL346 increased the expression level of Adamts4, which promotes recovery after infection, and decreased that of Tlr2." (PMID 38949757, 2024). "It is likely that TLR2 plays a major role in the recognition of Ad infection in the immediate early phase of infection (within 6 h of infection)." (PMID 38205184, 2024). "By confocal microscopy, ARM and WE strains have similar intracellular trafficking although LCMV-ARM infection appears to coincide with greater co-localization of early endosome marker EEA1 with TLR-2." (PMID 38675975, 2024). "By mimicking the natural route of S. aureus infection in patients with AD, our dry-skin mouse model further revealed that the exacerbated IL-33 release from an epicutaneous-infection with S. aureus was dependent on TLR2 signaling and necroptosis." (PMID 38319737, 2024). "Subsequently, TLR2 was solely reported to control and prevent bacterial expansions within the later stages of infection." (PMID 36911530, 2023). "After infection, PAMPs bind to the Toll-like receptor 2 (TLR2), TLR4, and TLR5 on the gut mucosal surface, activating the TLRs/NF-κB pathway." (PMID 37881635, 2023). "Naringenin, a flavonoid product, is known to modulate mouse J774 macrophages upon infection with C. trachomatis, through modulation of TLR2, TLR4, and CD86 receptors and down-streaming of the MAPK (p38) pathway." (PMID 36982245, 2023). "A study by Polari and coworkers described that in the context of human infection by L. braziliensis, the patient’s MΦ increased TLR2 and TLR4 and triggered TNF-α and IL-10." (PMID 37190011, 2023). "Previous studies have indicated that the GBS hyaluronidase (HylB) can enhance systemic infection by breaking down host hyaluronan into disaccharides that dampen protective TLR2 and TLR4 signaling." (PMID 37747229, 2023). "While TLR4 would impair and control the infection spreading throughout the initial stage of infection, the conger immune receptor, TLR2, was reported beneficial for reducing inflammatory levels associated with the infection." (PMID 36911530, 2023).
infection (continued). "Infection, the level of immunoreactivity for TLR2 became higher (red arrows), and gradually on the following days post-Acanthamoeba spp." (PMID 37242301, 2023). "In contrast, both age and TLR2 regulate the IgG and its subclasses, especially IgG2b production in healthy mice and IgG2b responses to infection as well as antigen-specific IgM levels." (PMID 37258615, 2023). "TLR-2 expression in DM increased after the infection with TB antigens as a protective immune response by the host against TB infection." (PMID 36903646, 2023). "Within the CNS, IL-10 is produced by resident microglia and astrocytes as well as infiltrating leukocytes during neuroinflammatory diseases and IL-10 production is elicited in response to TLR2 signaling during S. aureus craniotomy infection." (PMID 37179295, 2023). "We, therefore, examined the role of TLR2 signaling in the downstream cytokine response elicited by the SchuS4 ∆tolC mutant during BMMs infection." (PMID 37404047, 2023). "infection in different species, including bovine, via Toll-like receptor 2 (TLR2) binding and MyD88-dependent signaling." (PMID 36692289, 2023). "The mRNA expression level of Tlr-2 increased significantly upon infection with A. actinomycetemcomitans confirming the involvement of this gene in detecting this bacterium." (PMID 37929187, 2023). "Monocytes play a critical role in the early immune response to infection by directly recognizing PAMPs through their higher expression of mb-TLR2, which is consistent with previous findings." (PMID 38140264, 2023). "In line with previous data from SA biofilm infection models, biofilm CM of SA and SE induced a less pronounced upregulation of TLR-2 surface localization compared to planktonic CM." (PMID 37212952, 2023). "In agreement with this, we found that TLR2 signaling was required for increased release of IL-6 in response to infection with the Schu S4 ∆tolC mutant." (PMID 37404047, 2023). "CD36 can associate with TLR2/6 or TLR4/6 complexes and favor immune response in context of infection or sterile inflammation." (PMID 37996952, 2023). "In particular, IDV is known to stimulate the RIG-I/MDA-5 cytosolic receptor, whereas M. bovis is known to activate the TLR2 membrane receptor upon infection (29, 43, –, 45)." (PMID 36692289, 2023). "NF-κB (p65, RelB, c-Rel, NF-κB1, and NF-κB2) and MAPK (ERK, p38, and JNK) signaling pathways, as the downstream signals of TLR2 are essential immune molecules during infection that regulate the expression of inflammation cytokines." (PMID 37239946, 2023). "Our prior work has established the existence of proinflammatory responses that are critical for preventing S. aureus outgrowth during craniotomy infection; particularly the Toll-like receptor 2 (TLR2)-IL-1β axis and neutrophil action." (PMID 37179295, 2023). "TLR2 was differentially expressed at several time points, and most highly downregulated in crusted scabies at the beginning of infection." (PMID 37242301, 2023). "Of note, similar to TNF-α and IL-6, the quantity of IL-27 decreased when TLR-2 or TLR-4 were blocked prior to infection." (PMID 36863206, 2023). "Here we observed that both IgG1 and IgG2a levels were increased in all mice in response to the infection, but these responses were more induced in both young WT and TLR2−/− mice than in their aged counterparts." (PMID 37258615, 2023). "Porcine epithelial cell line IPEC-J2 infected with S. Typhimurium showed upregulated TLR2 mRNA expression 1.5 and 6 h post-infection." (PMID 38003758, 2023). "CYP27B1, the 25‐hydroxyvitamin D 1α‐hydroxylase, leads to production of active vitamin D3 at sites of infection, which is critical for the TLR2/1‐induced antimicrobial activity in macrophages infected with Mycobacterium tuberculosis." (PMID 38020709, 2023). "An increased mb-TLR2 expression trend was also detected in NK cells isolated from PBMCs after infection." (PMID 38140264, 2023).